CD38 (CD38 molecule)
Diseases named in the same sentence as CD38 in open-access papers (continued):
Sharing a sentence is not in itself a finding about the gene and the disease.
multiple myeloma (continued). "Daratumumab is an IgG1κ human monoclonal antibody commonly used to treat multiple myeloma, characterized by cancerous plasma cells and often leads to renal failure requiring kidney transplant, by depleting CD38-expressing plasma cells." (PMID 36294380, 2022). "We tested the capacity of these HLE-nano-BiKEs to mediate cytotoxicity against CD38-expressing multiple myeloma cell lines and primary myeloma cells from human bone marrow biopsies in bioluminescence and flowcytometry assays with NK92 cells as effector cells." (PMID 35651607, 2022). "Since CD38 is not only expressed on myeloma cells but also on other cells, some level of on-target off-tissue signal is expected when using CD38-specific nanobodies for in vivo imaging purposes." (PMID 36389758, 2022). "Substantial clinical improvement has been observed, especially with the combination of current myeloma therapeutic regimens and CD38-targeting antibodies." (PMID 36139103, 2022). "We verified specific and simultaneous binding to CD38 on myeloma cells, CD16 on NK cells, and to albumin." (PMID 35651607, 2022). "Myeloma that is refractory to an immunomodulatory agent, a proteasome inhibitor, and monoclonal anti-CD38 antibody treatment (triple-class refractory) myeloma has emerged as a pressing need to find new effective management strategies." (PMID 35877215, 2022). "In a study examining targeted therapy for MM, researchers used CD38-specific ssDNA aptamers selected by a hybrid SELEX process to efficiently target myeloma cells." (PMID 35056696, 2022). "The anti-CD38 monoclonal antibody daratumumab is the backbone of most anti-multiple myeloma (MM) regimens." (PMID 35359355, 2022). "The results revealed specific time- and dose-dependent cytolysis of CD38+ myeloma cell lines and effective depletion of CD38-expressing multiple myeloma cells from primary human bone marrow samples." (PMID 35651607, 2022). "Compelling evidence has been provided for the role of CD38 in directly promoting MM survival through mechanisms supporting bioenergetic plasticity of the myeloma cell." (PMID 36139103, 2022). "We report the generation of a fluorochrome-conjugated nanobody recognizing such an epitope of CD38 to detect myeloma cells under daratumumab therapy in vitro, ex vivo, and in vivo." (PMID 36389758, 2022). "The capacity of JK36AF680 to bind and detect CD38-expressing cells pretreated with daratumumab was evaluated on CD38-expressing tumor cell lines in vitro, on primary myeloma cells from human bone marrow biopsies ex vivo, and in a mouse tumor model in vivo." (PMID 36389758, 2022). "Daratumumab, a monoclonal antibody against CD38, was applied to treat multiple myeloma (MM) by inhibiting the growth of tumor cells expressing CD38." (PMID 35185886, 2022). "We generated nanobodies directed against CD38, a tumor marker that is overexpressed by multiple myeloma and other hematological malignancies." (PMID 36405759, 2022). "In newly diagnosed disease, the current treatment landscape for myeloma is such that with immunomodulatory agents, proteasome inhibitors, and CD38-targeting antibodies, one can achieve deep responses." (PMID 36389674, 2022). "Daratumumab is an approved immunotherapy for multiple myeloma that depletes CD38-expressing cancer cells." (PMID 36138193, 2022). "CD38 is a protein with multiple functions, as both a receptor and ectoenzyme that is overexpressed at every stage in myeloma." (PMID 35454812, 2022). "Daratumumab is a subcutaneously administered, anti-CD38 monoclonal antibody already approved for multiple myeloma, which is able to induce apoptosis in CD38 highly expressing cells." (PMID 35890078, 2022). "Of note, #5-CD38-IgG1 also recognized CD38 on patient-derived malignant plasma cells derived from BM MNC of three myeloma patients." (PMID 35784366, 2022). "Intriguingly, daratumumab, an anti–human CD38 monoclonal antibody used to treat myeloma, has been shown to target CD38-expressing Tregs." (PMID 35192548, 2022).
multiple myeloma (continued). "Daratumumab (DARA) is a CD38 antibody approved for treatment of MM as monotherapy or in combination with a number of standard of care anti-myeloma drugs." (PMID 36131131, 2022). "Phage antibodies #5 and #23 bound to B and/or T cell lymphoma/leukemia cells and were identified as CD38 and ICAM-1 antibodies, respectively, by using stably transfected CHO cell lines expressing one out of 10 individual human myeloma-associated antigens." (PMID 35784366, 2022). "Our data demonstrated that CD38KO NK cells have more prominent metabolic profile, increased killing mediated by ADCC against CD38+ multiple myeloma cell lines and patient derived samples and are protected from fratricide mediated by daratumumab." (PMID 35449580, 2022). "Isatuximab, an anti-CD38 antibody similar to daratumumab, is under investigation to treat the PCD underlying AL amyloidosis." (PMID 36606280, 2022). "The monoclonal antibody against CD38, daratumumab, has significant activity in patients with relapsed or refractory AL amyloidosis." (PMID 35410992, 2022). "Daratumumab, an anti-CD38 monoclonal antibody, has become the backbone of treatment of multiple myeloma and AL amyloidosis, being able to quickly drop the free light chains." (PMID 35326711, 2022). "The CD38-targeting antibody daratumumab has marked activity in multiple myeloma through direct anti-tumor effects and immunomodulatory activity." (PMID 34070044, 2021). "H929 is a B cell line with CD38 expression established from a malignant effusion in a patient with myeloma." (PMID 34162832, 2021). "Previous reports have demonstrated that residual myeloma cells are immature, have low CD38 expression, and are rich in integrin-related antigens." (PMID 34638353, 2021). "Apart from myeloma cells, CD38 is expressed in several normal tissues including cardiomyocytes and immune cells of lymphatic origin and macrophages." (PMID 34680206, 2021). "Functionality against models of multiple myeloma was demonstrated recently in pre-clinical in vitro and in vivo studies, both as monotherapy and in combination with daratumumab (anti-CD38) elotuzumab (anti-SLAM7) or anti-CD19." (PMID 34897554, 2021). "The intravenous anti-CD38 monoclonal IgG1 antibody daratumumab has proven its capability to deplete clonal plasma cells in myeloma." (PMID 33801294, 2021). "Considering the extensive and high‐level expression of CD38 in myeloma cells, monoclonal antibodies targeting CD38 have been developed, which have proven significantly active in the treatment of MM." (PMID 34752645, 2021). "This anti‐CD38‐directed monoclonal antibody is approved for the treatment of multiple myeloma, but has shown promise in the treatment of relapsed/refractory AL amyloidosis patients as well." (PMID 33347707, 2021). "Daratumumab, a CD38-targeting monoclonal antibody for the treatment of multiple myeloma (MM), has potent single agent activity and a favorable toxicity profile." (PMID 34070044, 2021). "Although anti-CD38 monoclonal antibodies have improved the prognosis of relapsed/refractory multiple myeloma (RRMM), some patients still experience early relapses with poor outcomes." (PMID 34503133, 2021). "CD38 is intermediately expressed on both myeloma cells and healthy hematopoietic cells which elevates the risk of on-target/off-tumor toxicity." (PMID 33781320, 2021). "CD38, found throughout the immune system especially natural killer and PC, is highly expressed in multiple myeloma cells." (PMID 34093594, 2021). "CD38 represents a promising target for monoclonal antibody (mAb)-based immunotherapy of multiple myeloma (MM)." (PMID 34539634, 2021). "Poor remission status, older age, type of anti-myeloma therapy and anti-CD38-directed therapy, in particular, have consistently been identified as additional factors impacting vaccination response." (PMID 34884200, 2021). "The conventional CD38-specific mAb daratumumab and isatuximab have demonstrated their clinic efficacies in multiple myeloma." (PMID 33567640, 2021).
multiple myeloma (continued). "Anti-CD38 mAbs eliminate multiple myeloma targets by mediating CDC, ADCC, ADCP, FCγR-mediated cross-linking–induced apoptosis and nicotinamide adenine dinucleotide (NAD+) depletion." (PMID 33807678, 2021). "Altogether, this has triggered the development of several CD38 antibodies to treat multiple myeloma." (PMID 34093594, 2021). "In the last decade, CD38-targeting immunotherapies, such as daratumumab, have been recognized as a key component in the treatment of myeloma by inducing an important plasma cell depletion." (PMID 34093594, 2021). "Isatuximab (Isa) is a monoclonal IgG1 antibody that targets a specific epitope on CD38 using several different mechanisms of action against multiple myeloma." (PMID 34680184, 2021). "They possessed an increased phagocytic capacity enabling a superior antibody-dependent phagocytosis of multiple myeloma (MM) and lymphoma cells that were treated with anti-CD38 or anti-CD20 mAbs, respectively." (PMID 34021248, 2021). "On the other hand, CD38 was also known to facilitate cell adhesion, and CD38 expression in multiple myeloma cells was positively correlated with TNT anchor points in cocultured BMSCs,84 indicating that CD38 expression is linked to nanotube attachment." (PMID 33589598, 2021). "We appraised the impact of daratumumab (DARA)- and isatuximab (ISA)-based DFMT to crosslink CD38 receptors on CD38+ lymphoma (Raji, Daudi) and multiple myeloma cells (RPMI 8226, ANBL-6)." (PMID 34361811, 2021). "Lessening involvement of Treg in suppressive CD39/CD73 adenosine pathway is likely compensated by alternative adenosine pathway involving NAD(+)-consuming enzyme CD38 which is active in the BM niches of myeloma and correlates with progression of myeloma." (PMID 33708212, 2021). "Daratumumab is a human specific IgG1 anti-CD38 approved as a single agent or in combination regimens for the treatment of relapsed/refractory multiple myeloma." (PMID 33727923, 2021). "Similar to CD38 monoclonal antibodies, limited single-agent efficacy has led to indatuximab ravtansine being investigated in combination with standard myeloma regimens." (PMID 33922567, 2021). "Several hematologic malignancies also express varying levels of CD38, such as multiple myeloma (MM), chronic lymphocytic leukemia (CLL), non-Hodgkin's lymphoma (NHL), acute lymphoblastic leukemia (ALL), and acute myeloid leukemia (AML)." (PMID 33820568, 2021). "They possessed an increased phagocytic capacity enabling superior antibody-dependent phagocytosis (ADPC) of multiple myeloma and lymphoma cells that were treated with anti-CD38 or anti-CD20 mAbs." (PMID 34021248, 2021). "Daratumumab is an IgGκ monoclonal antibody targeting CD38, which is highly expressed in plasma cells, plasmablasts, B cells in early maturation stages, and myeloma cells." (PMID 35003106, 2021). "It triggers ADCC, CDC, and TAM in CD38+ multiple myeloma cells in both sensitive and drug resistance patients, modulates the enzymatic activity of CD38, and reduces adenosine levels." (PMID 33727923, 2021). "Daratumumab is a monoclonal antibody directed against the transmembrane glycoprotein CD38 expressed on plasma cells and lymphoplasmocytes, with a proven efficacy in multiple myeloma." (PMID 33732266, 2021). "The monoclonal anti-CD38 daratumumab has taken a central place in the different treatment regimens for newly diagnosed and relapsed, refractory myeloma." (PMID 34203012, 2021). "Prior studies have shown that CD38 is an effective treatment for multiple myeloma patients with a striking reduction of RF, ANCA, and ANA titer." (PMID 35003106, 2021). "Daratumumab, an anti-CD38 monoclonal antibody, is currently approved for heavily pretreated relapsed and refractory multiple myeloma patients, being a promising agent to be tested in refractory prostate cancer." (PMID 34638258, 2021).
multiple myeloma (continued). "CD38+ CD138+ plasma cells and CD38+ CD138+ CD56+ CD19– myeloma cells were mobilized up to three-fold increases compared with baseline values in the peripheral blood." (PMID 33918655, 2021). "Both daratumumab and isatuximab have been shown to effectively induce myeloma cell death via Fc-dependent mechanisms of action and the depletion of CD38+ immunosuppressive cells." (PMID 33467713, 2021). "We present two examples – one of CCR2/CD192, a chemokine receptor expressed on monocytes, and CD38, a glycoprotein expressed on the surface of multiple immune cell types, and a target of therapies for multiple myeloma." (PMID 33835024, 2021). "Daratumumab (Dara) is a humanized IgG1 (ĸ subclass) monoclonal antibody targeting the CD38 epitope, which has been approved by the USA Food and Drug Administration for the treatment of patients with relapsed and newly diagnosed multiple myeloma." (PMID 34987512, 2021). "Over the last two decades, the additions of proteasome inhibitors (PIs), immunomodulating agents (IMiDs), and anti-CD38 antibodies to the multiple myeloma treatment arsenal have improved survival materially." (PMID 35127532, 2021). "Remission-inducing therapy is an unmet need for patients with myeloma that is refractory to proteasome inhibitors, immunomodulatory agents, and an anti-CD38 monoclonal antibody, as well as to prior autologous stem cell transplantation." (PMID 34072068, 2021). "We next asked if the addition of IL6, a well-known STAT3 activating cytokine in myeloma, will help improve CD38+ cell viability." (PMID 34201211, 2021). "To boost their anti-tumor activity, we combined allogeneic NK cells with the approved anti-cluster of differentiation 38 (CD-38) monoclonal antibody Daratumumab to obtain a synergistic therapeutic effect against incurable multiple myeloma." (PMID 33919155, 2021). "Otherwise, CD38 blocking with Isatuximab in Treg cells from Myeloma Multiple patients has demonstrated a reduced IL-10 expression and a higher amount of IFN-γ expression in CD8+ T-cells." (PMID 34769406, 2021). "In multiple myeloma mitochondrial transfer occurs through formation of nanotubules which was dependent on CD38 expression." (PMID 34764342, 2021). "Initially, this technique was used in primary NK cells to disrupt the CD38 gene, aiming to prevent fratricide of NK cells when they were used in combination with daratumumab (anti-CD38), as CD38 is expressed both on NK cells and multiple myeloma and AML cells." (PMID 33933160, 2021). "In the last few years, an increasing number of studies in patients with multiple myeloma have found that CD38+ Treg cells are more suppressive than CD38− Treg cells and antagonist antibodies can block their inhibitory activity." (PMID 34769406, 2021). "Histone deacetylase (HDAC) inhibitors (Panobinostat, Ricolinostat) upregulate CD38 RNA levels and CD38 surface expression on multiple myeloma cells, thus disrupting latency of the malignant cells." (PMID 33727923, 2021). "Currently available anti-myeloma agents, such as PIs, IMiDs, and anti-CD38 MoAb, work for the BM microenvironment and show an antimyeloma effect." (PMID 33435539, 2021). "Considering the microenvironment around myeloma cells, initial treatment encompassing IMiDs, PIs, anti-CD38 MoAb, and ASCT is important." (PMID 34638353, 2021). "Daratumumab reduces suppressive cell types in the multiple myeloma tumor microenvironment as it reduces CD38 expression, but as treatment progresses, it also increases the resistance to treatment." (PMID 33727923, 2021). "The authors further demonstrated that myeloma cells have an increased dependence on the membrane glycoprotein CD38, and that mitochondrial transfer was partly regulated through a CD38-dependent mechanism." (PMID 33144695, 2021). "Darzalex (daratumumab), an FDA-approved CD38 inhibitor for mono- and combination therapy of multiple myeloma, binds to CD38, blocks the growth of the cells and induces their death." (PMID 34885748, 2021).
multiple myeloma (continued). "Antibody-based therapies targeting CD38 are currently used as single agents as well as in combination regimens for multiple myeloma, a malignant plasma cell disorder." (PMID 34727950, 2021). "The first anti-CD38 monoclonal antibody becoming available in multiple myeloma was daratumumab, and in a couple of years, a few prospective trials and many retrospective studies assessed its role also in AL amyloidosis." (PMID 33806310, 2021). "CD38 is also expressed on myeloma cells and regulatory T cells; the depletion of all three cellular compartments is thought to underpin the promising clinical efficacy of this class of drugs." (PMID 33777050, 2021). "CD38 is a glycoprotein that is expressed on AML cells as well as plasma cells; anti-CD38 antibodies such as daratumumab and isatuximab are already approved in the treatment of multiple myeloma." (PMID 34829860, 2021). "Daratumumab (DARA) is an FDA-approved high-affinity monoclonal antibody targeting CD38 that has shown promising therapeutic efficacy in double refractory multiple myeloma (MM) patients." (PMID 34611478, 2021). "The most relevant is CD38, which is expressed on myeloma cells, and it is used as an anti-CD38 target." (PMID 34503142, 2021). "Triple‐class‐refractory multiple myeloma (MM) describes MM refractory to proteasome inhibitors, immunomodulatory agents, and anti‐CD38 monoclonal antibodies." (PMID 35846096, 2021). "The anti-CD38 antibody daratumumab, approved for use against multiple myeloma, was augmented after fusion to either the μtp C575S or μtp, demonstrating that this technology can be applied to a wider range of targets beyond CD20." (PMID 34475514, 2021). "Regulatory B cells (Bregs) identified by the CD19+CD24+CD38+ phenotype are an important immunosuppressive components for myeloma, as they prevent immune effector cells from homing and interacting with targeted tumor cells." (PMID 33356013, 2021). "These CD38-directed CAR-NK cells further displayed their activities against primary multiple myeloma cells from eight patients." (PMID 33567640, 2021). "One potential target is CD38, an ecto-enzyme that is highly expressed on the surface of malignant plasma cells in multiple myeloma." (PMID 34131806, 2021). "To maximally harness their therapeutic potential for multiple myeloma (MM) treatment, we here armed iNKT cells with chimeric antigen receptors (CAR) directed against the MM-associated antigen CD38 and the plasma cell specific B cell maturation antigen (BCMA)." (PMID 33499253, 2021). "New treatment options for multiple myeloma are rapidly evolving, with the approval of anti-CD38 antibodies such as daratumumab and isatuximab, further improving outcomes." (PMID 34145225, 2021). "Increasing the expression of CD38 on target cells or neutralizing CD38 on effector cells changed the equilibrium between target and effector cell lysis and promoted multiple myeloma cell death." (PMID 34203012, 2021). "And the FDA has approved two CD38 antibodies (Daratumumab and Isatuximab) for the treatment of multiple myeloma due to the promising preclinical and clinical activities of CD38 in hematopoietic system." (PMID 34226519, 2021). "Daratumumab, a human IgG1 antibody that targets CD38 and has a direct antitumor and immunomodulatory activity, attaches to the CD38 protein found on the surface of myeloma cells, thereby enabling the immune system to target and kill it." (PMID 33669402, 2021). "Previously, CD38+ Treg cells have been defined as a highly suppressive subset in patients with multiple myeloma and have shown an increased ability to inhibit immune response." (PMID 34769406, 2021). "MM cells express many markers; among them, CD38 molecules are uniformly and highly expressed on the surface of myeloma cells." (PMID 34513682, 2021). "Multiple myeloma is a type of cancer where malignant plasma cells overexpressing CD38 accumulate in the bone marrow." (PMID 33727923, 2021).